TWIST1 (twist family bHLH transcription factor 1)
Diseases named in the same sentence as TWIST1 in open-access papers (continued):
Sharing a sentence is not in itself a finding about the gene and the disease.
tumor (continued). "Although Twist1 is known to facilitate tumour progression by suppressing the immune system, there are no studies examining the relationship between Twist1 and the immune checkpoint VISTA." (PMID 40344465, 2025). "RNase digestion alone failed to alter Twist1 mRNA expression levels in SDEVs from tumor-bearing mice, whereas combined treatment with Triton X-100 substantially decreased Twist1 mRNA abundance." (PMID 40963917, 2025). "AR expression was positively correlated with tumor-originated vasculogenesis in ccRCC patients, suggesting a tumor-promoting role, which was validated in in vitro experiments, possibly through modulating the lncRNA-TANAR/TWIST1 signaling pathway." (PMID 41228208, 2025). "In BC cells, the signaling pathways TNFα/NFκB and IL6/STAT3 are known to promote tumor progression via activation of key EMT-related transcription factors, such as Snail Family Transcriptional Repressor 1 (Snail1), Twist-related protein 1 (Twist1), and Zinc finger E-box binding homeobox 1 (ZEB1)." (PMID 40807456, 2025). "Through gene expression analyses of colon tissue, we identified significant increases in markers of tumor progression and microenvironment regulation, including LGR5, TWIST1, SNAIL, IL-8, CCL2, and COX2, in the colon of PSC patients compared with those with IBD alone." (PMID 40476597, 2025). "Similarly, in 5-FU-exposed isolated HT-29 cells, all EMT-related genes, including TWIST1, SNAIL1, ZEB1, Vimentin, and N-cadherin, showed upregulation than parental cells, while the tumor and EMT suppressor protein E-cadherin experienced downregulation." (PMID 40251609, 2025). "Bulk RNA-seq analysis of tumor ECs derived from three human patients with GBM confirmed specific knockdown of Twist1, but not Twist2, and identified about 400 differentially expressed genes in Twist1-knockdown ECs." (PMID 38416830, 2024). "Combined expression of WNT ligands (WNT3A, WNT4, WNT7B, WNT9A, WNT10A, WNT11) in BRCA patient tumours has a positive correlation (R = 0.27, p value = 0) with the combined expression of key EMT-inducing transcription factors SNAI1, SNAI2, ZEB1, ZEB2 and TWIST1." (PMID 38678032, 2024). "TGF-β can induce SOX5 expression through Smad3 phosphorylation, and SOX5 can promote the expression of Twist1, resulting in overexpression of Twist1 and inducing EMT to promote tumor metastasis, while targeting SOX5 can effectively delay TGF-β signal-induced EMT." (PMID 38835366, 2024). "Protein levels were verified by extracting subcutaneous tumor proteins, where the expression levels of the EMT-related proteins N-cadherin, TWIST1 were decreased and E-cadherin was increased in the shYTHDF2 group, while the opposite trend was shown in the YTHDF2 overexpression group." (PMID 39593172, 2024). "Because of these manifold effects on both the tumor cells and the TME, we used overexpression of Snai1 and Twist1 to test the potential of our platform to evaluate the effect of the misregulation of individual genes in different cellular components of the tumor." (PMID 38678014, 2024). "MSK-LX29 tumor was derived from the patient with EGFR mutant NSCLC who developed resistance after 3 months of erlotinib treatment with an acquired MET amplification and had the highest TWIST1 expression." (PMID 38485737, 2024). "It is possible that 8‐oxoG/OGG1 could drive tumour metastasis through induction of not only SYT7, but also SNAIL1 and TWIST1." (PMID 39235072, 2024). "Genetic or pharmacological ablation of Twist1 reverses Mφ-mediated immunosuppression and enhances T cell infiltration and activation, leading to reduced GBM growth and extended mouse survival, and sensitizing tumor to chimeric antigen receptor T immunotherapy." (PMID 38416830, 2024).
tumor (continued). "Furthermore, our study reveals a sequential transcription activation mechanism that leads to Twist1-inducible SATB1 transcription and SATB1-inducible OPN transcription, providing molecular insight into SATB1-mediated tumor immunity." (PMID 38416830, 2024). "Our results demonstrated a reversal of Snail, Slug, and Twist1 overexpression in melittin-treated CRC cells, suggesting that melittin inactivates these transcription factors, inhibits EMT, and prevents further tumor cell dissemination from the primary site." (PMID 39519238, 2024). "Analysis of the IHC cohort showed positive correlations between Slug, Twist1, or vimentin expression and PD-L1 expression and a negative correlation between E-cadherin expression and PD-L1 expression by tumor cells in patients with PD after ICI therapy." (PMID 38729997, 2024). "Twist1 knockout did not affect tumor EC proliferation, implicating a main regulatory function of Twist1 in the expression of immunosuppressive factors but not in vascular structure." (PMID 38416830, 2024). "Transcription factors like ZEB1, TWIST1 and NAI1, all of which could be potentially used for tumor therapy, regulate EMT-mediated tumor metastasis and drug resistance." (PMID 39877159, 2024). "Meanwhile, the increase in MMP-2 MMP-9, SNAI1 and TWIST1 protein levels in the IL-22 group suggests that IL-22 may regulate MMP expression by activating the PI3K/AKT signaling pathway, enhancing tumor cell invasion and metastasis." (PMID 39073546, 2024). "Twist1 transcriptionally activated Thymidine Phosphorylase (TP), which promoted HCC metastasis and VM formation via the Warburg effect, alleviating the deteriorated tumor microenvironment and bolstering tumor progression and metastasis." (PMID 37784111, 2023). "By the way, ECM stiffness transduces mechanical signal to TWIST1, then destroys the interaction between TWIST1 and Ras-GTPase activating protein SH3 domain-binding protein 2 (G3BP2), which induces nuclear import of TWIST1 and EMT in tumor." (PMID 36906534, 2023). "We find this unlikely, since Twist1 expression did not correlate with MF staging or tumor cell density or percentage of reactive lymphocyte." (PMID 36900319, 2023). "Next, we detected epithelial and EMT marker gene expression in xenograft tumor tissues, and found that depletion of KLF16 in implanted cells dramatically reduced the expression of KLF16, Twist1, and mesenchymal markers vimentin, with an increase in the epithelial marker E-cadherin." (PMID 36639679, 2023). "In adenocarcinoma, miR-9-5p exerts a tumour suppressive role and the epithelial-to-mesenchymal transition phenotype is achieved by low levels of miR-9-5p, which enable the upregulation of CDH2 via the transcription factor TWIST1." (PMID 36961325, 2023). "The results suggested that largerer tumor size (OR=4.397, p = 0.026), higher ypT stage (OR=6.260, p = 0.036), higher expression of FAP in CAF (OR=16.905, p = 0.004), and higher expression of Twist1 (OR=14.238, p = 0.001) were independent predictors for the pathological response, respectively." (PMID 37277751, 2023). "The IL6/JAK2/STAT3 signaling axis is best studied in the context of tumor metastasis and tumor pathology since it induces epithelial–mesenchymal transition (EMT), resulting in tumor metastasis by promoting the expression of EMT-inducing transcription factors, such as Snail, ZEB1, JunB, and Twist1." (PMID 38203502, 2023). "While TJP1 expression in tumour cells is repressed in activated EMT, we found that the expression levels of SNAI2 and TWIST1 were significantly decreased in Ex-MaPac107 and the expression of ZEB1 was significantly increased in Ex-MaPac107 compared with Pri-MaPac107." (PMID 37686338, 2023). "Our results revealed that Rab31 promotes tumor metastasis and cisplatin resistance in STAD through Twist1-mediated EMT, which suggests that Rab31/Stat3/MUC-1/Twist1 pathway is a promising therapeutic target to overcome resistance to cisplatin and metastasis in STAD." (PMID 36781842, 2023).
tumor (continued). "Conversely, enforced TWIST1 expression in a mouse MM cell line enhanced its migration in vitro and its dissemination/invasiveness in vivo, but did not impact on overall tumor growth and proliferation." (PMID 37600794, 2023). "Indeed, mRNA and protein expression levels of an epithelial gene (CLDN1) were decreased, while those of mesenchymal (VIM) and EMT regulator (Snail, Twist1, ZEB1, and ZEB2) genes were increased in tumor cells." (PMID 35618735, 2022). "Conversely, RBX1 overexpression remarkably raised the TWIST1 protein level in the TNBC cells, whereas the TWIST1 mRNA expression was not affected in RBX1 knockdown or overexpression in TNBC tumour cells." (PMID 35802537, 2022). "Nearly all samples (regardless of tumor or non-tumor), particularly those labeled blue, displayed an inverse correlation between the expression of TWIST1 and SPOP." (PMID 36115849, 2022). "It has revealed that EMT-TF Twist1 is competent at dedifferentiating epithelial type tumor cells into non-proliferative, mobile mesenchymal cells with stemness characteristics." (PMID 35308223, 2022). "Solitary genetic ablation of Snail or Twist1 does not significantly alter the cellular composition of PDAC tumours in murine models, though does render tumours more chemosensitive." (PMID 36088504, 2022). "TWIST1, a basic helix-loop-helix (bHLH) transcription factor, is the most important epithelial-mesenchymal transition (EMT) gene involved in embryonic development, tumor progression, and metastasis." (PMID 35052775, 2022). "Reduction of Twist1 can reversibly redifferentiate the EMT cells into epithelial-phenotypes cells at the site of metastasis where the cells start colonizing and proliferating, potentially contributing to inhibiting tumor metastasis and invasion." (PMID 35308223, 2022). "Importantly, the tumor spheroids derived from the MCW-OV-SL-3 cell line expressed high levels of c-Kit, PROM1, ZEB1, SNAI, VIM, and Twist1 compared to 2D monolayer cells." (PMID 35205706, 2022). "The molecular etiology of EC and the pathogenic role of the demonstrated here overexpression of MYC, NR5A2, SNAI1, and TWIST1 in tumor-adjacent tissues is not clear." (PMID 36140779, 2022). "For example, studies have reported that over-expression of EMT signal regulators (such as TWIST1 and MMPs) can promote immune infiltration in TME, which promotes tumor cell immune escape Tumor immune escape is a major contributor to tumor malignancy, poor prognosis, and treatment failure." (PMID 36034778, 2022). "Knockdown of KLF4 and BMI1 reduced the number and size of tumor sphere formation and tumor-initiating ability, suggesting that both KLF4 and BMI1 may contribute to inducing stem-like property and metastasis by TWIST1-JAGGED1-NOTCH-KLF4 signaling in HNC." (PMID 36553636, 2022). "TWIST1 acts as an EMT regulator and promotes tumor progression through distinct mechanisms." (PMID 35052775, 2022). "miR-361-5p targets Twist1 and cramps HCC cell proliferation, migration, invasion, and tumor growth." (PMID 34983307, 2022). "In addition, QFG treatment inhibited EMT and induced autophagy progression in CRC tumor cells, including that QFG upregulated the expression of E-cadherin, beclin-1, and LC3-II, but downregulated the expression of N-cadherin, vimentin, TWIST1, and p62." (PMID 34887935, 2021). "Finally, we assessed PCK1, c-Myc, Twist1, E-cadherin expression and KAT5 O-GlcNAcylation in 48 paired human HCC tissues and tumor-adjacent tissues." (PMID 34650217, 2021). "TWIST1 and CD105, which contribute to tumor malignancy, are overexpressed in cancers." (PMID 33752711, 2021). "Moreover, by Multivariate analysis using Cox’s proportional hazard model, high PD-L1 (p < 0.01), TWIST1 (p < 0.03), TIMP2 (p = 0.11) expression were independent and significant prognostic factors for tumor recurrence in NMIBC patients." (PMID 34885101, 2021).
tumor (continued). "In addition to regulating the transcription of TWIST1, it has been reported that KAT5 increases the stability of c-Myc through acetylation of c-Myc, thereby promoting tumor invasion and metastasis." (PMID 34650217, 2021). "TWIST-1 immunohistochemical analysis showed a lack of statistical significance in the number of positive cells on the invasive front of the tumor compared with the control tissues." (PMID 34638929, 2021). "TWIST1 plays a role in ES metastasis, as its suppression reduces metastasis but does not affect the development of the original tumor." (PMID 34440137, 2021). "Expression of TWIST1 and TOX is frequently increased in tumor T cells from CTCL patients." (PMID 33941102, 2021). "In addition, SPZ1 homodimers activate TWIST1 expression and are acetylated by TIP60 to form a heterodimeric SPZ1-TWIST1 complex, which promotes EMT and initiates tumor metastasis." (PMID 34749766, 2021). "Current research suggests that EMT transcription factors like SNAI1, TWIST1 and ZEB1 may contribute to the promotion of tumor metastasis and drug resistance by EMT." (PMID 35127731, 2021). "Moreover, Twist1 needs to induce Slug to suppress the epithelial branch of the EMT program and Twist1 and Slug act in concert to promote the mesenchymal arm of EMT and tumor metastasis." (PMID 33297508, 2020). "KLF4 wasdown-regulated in both tumor samples and mammospheres.Meanwhile, expression of NANOG was not changed inmammospheres, but it was down-regulated in tumors.Among EMT-related genes, CDH2, SNAIL1, TWIST1/2 andZEB1 were also overexpressed in mammospheres." (PMID 31376329, 2020). "RT‐qPCR results showed that, compared with the xenograft tumor zebrafish model group, FH could significantly reduce Snail2, ZEB2, TWIST1, and TGFβ1 mRNA expression (P < .01, 0.05)." (PMID 32037729, 2020). "Furthermore, in the tumor-bearing mouse model, we detected low levels of IGF1 and TWIST1 expression in tumors originating from MCF-7 cells transfected with anti-RCC2 shRNA." (PMID 32565805, 2020). "To evaluate if cytokines secreted by cancer cells mediate MYC and Twist1 driven macrophage recruitment and polarization, we evaluated the impact of tumor cell derived conditioned media on non-polarized macrophage cell lines." (PMID 31933479, 2020). "Taken together, we might speculate that HEK-EBNA293-VEGF-D cells underwent EMT-like processes driven by increased number of cells expressing TWIST-1 and ZEB-1 at the tumor periphery, thus acquiring an invasive phenotype." (PMID 33085676, 2020). "Orthotopic implantation of MYC/Twist1- but not MYC-HCC tumor cells in NSG mice led to pulmonary and intrahepatic metastases with extensive macrophage infiltration." (PMID 31933479, 2020). "Western blotting showed that compared with the EMT model group, FH could significantly increase E‐cadherin and reduce Snail2, ZEB2, TWIST1, and TGFβ1 protein expression in TNBC xenograft tumor zebrafish (P < .01.05)." (PMID 32037729, 2020). "Conditioned media from TAMs isolated from MYC/Twist1-HCC but not MYC-HCC increased the invasiveness of both MYC- and MYC/Twist1-HCC tumor cells in vitro." (PMID 31933479, 2020). "Moreover, by analysing the GSE37364 datasets, we found that cyclin D1, CDK4, and Twist1 were significantly up-regulated in CRC tissues, whereas E-cadherin was significantly down-regulated in CRC tissues when compared with the non-tumour tissues (all p < 0.05)." (PMID 31772673, 2019). "Further, the SPZ1 homodimer activates TWIST1 expression and is acetylated by TIP60 forming the SPZ1–TWIST1 heterodimeric complex, which activates the expression of downstream EMT markers and initiates tumor metastasis." (PMID 30154425, 2019). "(a) RNA-seq mRNA expression data from the TCGA and GTEx database was used to compare Twist1 expression between in PCa tumors (T) (n = 492) and their non-tumor counterparts (N) (n = 152)." (PMID 31383001, 2019).
tumor (continued). "Accordingly, SLC12A5 was highly expressed in 17 out of 24 TWIST1 strong tumor tissue samples, and in 5 out of 18 tumor tissue samples with weak TWIST1 expression; ZFHX4 was highly expressed in 19 out of 24 TWIST1 strong tumor tissues, and in 6 out of 18 tumor tissue samples with weak TWIST1." (PMID 31645542, 2019). "TWIST1 was shown to be expressed in invasive primary tumors in SPZ1 transgenic mice and in noninvasive neoplastic lesions, suggesting that TWIST1 exerts a positive regulatory effect on target genes involved in tumor initiation and progression." (PMID 30154425, 2019). "Hence, TP, when transcriptionally activated by Twist1, promotes HCC VM formation and metastasis through the pentose Warburg effect and contributes to tumor progression." (PMID 30674871, 2019). "This phenotype would have mesenchymal features, that would result as a downstream effect of the STAT3-RAS-MAPK-ERK-MYC pathway, regulating ID3/E47 interactions and promoting tumor cell migration and invasion through expression of mesenchymal genes such as MMPs, SNAIL1, TWIST1, and PRRX1." (PMID 30899759, 2019). "Statistically significant differences in co-expression of PRMT1 with ZEB1, RUNX1 and TWIST1 were observed only in ccRCC, but not in other analyzed tumor types." (PMID 31655611, 2019). "In addition to a high percentage of VIM-positive tumour cells, MSCCs had a low percentage of CDH1-positive cells and a high percentage of TWIST1-, ZEB1- and ZEB2-positive cells, characteristic of EMT." (PMID 31080552, 2019). "TWIST1 overexpression alone or co-expression with SPZ1∆B in Hep 3B cells showing low SPZ1 expression did not significantly activate EMT markers' expression, indicating the importance of the SPZ1–TWIST1 complex in tumor cell metastasis." (PMID 30154425, 2019). "Indeed, suppression of Snail1, Twist1, or Prrx1 attenuates the EMT and promotes the colonization of the metastatic site by tumor-initiating cells." (PMID 31569731, 2019). "Both TWIST1 and MMP9 play vital roles in EMT and tumor metastasis." (PMID 29348395, 2018). "We suggest that PLA2R1-regulated expression of FN1, TWIST1, and CDK6 might be accountable for the cell type-dependent impact of PLA2R1 in tumour cell survival and growth." (PMID 30542512, 2018). "Consistent with the RNA-sequencing and RT-PCR results, Chi3l1 KO mice had increased mRNA for anti-tumor immunity molecules including CTSE, TRAL, IFNγ, T-bet, Perforin, and Granzyme B, while the expression of Th1-inhibitory molecules such as Twist1 and SOCS1 was significantly reduced." (PMID 29403003, 2018). "EMT promotes invasive cell behavior by generating invadopodia on the membrane of the transitioning mesenchymal cells, a process induced by platelet-derived growth factor (PDGF) signaling; Twist1 activation induces PDGF receptor α and mediates PDGF signaling and tumor cell invasiveness." (PMID 30463358, 2018). "Since Notch1 and Twist1 play an important role in EMT and tumor progression, we examined whether there is a correlation between Notch1 and Twist1 in EMT status." (PMID 28035069, 2017). "Studies in human cell lines further investigated the physiologic targets of miR106a, and showed that miR106a could target tumor-suppressor genes, such as RUNX3, Twist1, pRB and E2F1." (PMID 27926519, 2017). "Meanwhile, considering that several studies reported miR-361-5p to act its function by targeting some other factors, such as Twist1, VEGFA and FOXM1, it remains to be explored whether other targets may contribute to the anti-tumor effect of miR-361-5p." (PMID 29132384, 2017).